MYH2 (myosin heavy chain 2)
Diseases named in the same sentence as MYH2 in open-access papers (continued):
Sharing a sentence is not in itself a finding about the gene and the disease.
cancer (14 papers, 2014 to 2025). A tumor composed of atypical neoplastic, often pleomorphic cells that invade other tissues. "Lithium chloride prevented wasting in myotubes cultured with cancer cell-conditioned media, maintained the expression of the muscle fiber contractile protein, myosin heavy chain 2, and inhibited the upregulation of the E3 ubiquitin ligase, Atrogin-1." (PMID 33925786, 2021). "Conditioned media from cancer-stimulated CAF (CAF CCM) was effective at inducing myotube atrophy in vitro, as shown by reduced myotube diameter, upregulated atrogin-1, and lower MYH2 levels." (PMID 41392310, 2025). "Interestingly, tumour‐induced alterations in the expression of Atrogin1, MuRF1, Pik3r1, Pdk4, Myh4, Myh2 and Myh1 were attenuated in EDA2R‐deficient muscles, implying that the EDA2R pathway contributes to the reprogramming of muscle gene expression during cancer cachexia." (PMID 39001644, 2024). "The study also highlights the roles of specific proteins (MYH2, MYL1, MYL2, MYH7) and microRNAs (such as hsa-let-7d-5p) that are the potential biomarkers in cancer progression founded on several analyses." (PMID 39656775, 2024). "Through pan-cancer analysis, we found that MYH1, MYH2, and MYH7 are dysregulated in cancers, including HNSC." (PMID 37340028, 2023). "We can observe that although MYH1, MYH2, and MYH7 were dysregulated in some of the cancers, their expression levels are very low, except for HNSC." (PMID 37340028, 2023). "Among cancer and precancerous lesions glycoproteins, we further highlight seven glycoproteins found in high-grade dysplasia as well as cancer (IGHG1, CPA2, MYH2, AZU1, PRTN3, CA1, SMPDL3B), holding potential for non-invasive detection of aggressive traits." (PMID 38612533, 2024).
tumor (10 papers, 2010 to 2024). "An enrichment analysis with Toppgene revealed that over 10 of the 17 significantly upregulated genes in the tumours of the female mice were skeletal muscle genes such as Acta1, Actn3, Myh2, Myh4 and Des." (PMID 37840045, 2023). "However, DOE treatment at two concentrations could reverse the effect of muscle atrophy induced by a CT26 tumor through a reduced expression level of Atrogin1 and an increased expression level of MYH2 compared with CT26-bearing mice, which received diluent only." (PMID 39519503, 2024). "Myosin genes MYL1, MYL2, MYH2, and MYH7 were proved significantly down-regulated but as unfavorable prognostic markers and related with tumor stages or grades in HNSCC." (PMID 37679666, 2023). "Since GATA3 mutants compared with non-mutant tumor samples did not indicate any difference in expression of MYH2, its lower expression in tumor samples may be resulted due to the tumor environment." (PMID 33462316, 2021). "Similar to MYH2, CKM (Muscle type of CK) is down-regulated in tumor (GATA3 mutant and non-mutant) tissues." (PMID 33462316, 2021).
colorectal (1 paper, 2022). "Additionally, a MYH2 gene variant increased the IBM risk in Japanese patients, and MYH2 was involved in colorectal carcinogenesis." (PMID 35806366, 2022).
infection (1 paper, 2020). The state of being infected such as from the introduction of a foreign agent such as serum, vaccine, antigenic substance or organism. "This cluster contained Acta1, encoding smooth muscle actin, as well as the actin crosslinking protein gene Actn3 and two myosin genes (Myo1h and Myh2), suggesting that both infection and Muc1 knockout disrupt the cytoskeleton." (PMID 32793510, 2020).
kidney disease (1 paper, 2013). "Sequence variants in MYH9 encoding myosin heavy chain 2A have been associated with two forms of kidney disease." (PMID 23874454, 2013).
MYH2 also shares sentences with these, for which no sentence is quoted: metabolic disease (2 papers); Obesity (2); Pancreatic Cancer (2); type 2 diabetes (2); amyloidosis (1); Bardet-Biedl syndrome (1); bladder cancer (1); co-infection (1); distal arthrogryposis (1); epileptic encephalopathies (1); External ophthalmoplegia (1); Feingold syndrome type 1 (1); gastric cancer (1); heart disease (1); Intellectual disability (1); ischemia (1); ischemic stroke (1); leiomyosarcoma (1); lung squamous cell carcinoma (1); myotonic dystrophy type 1 (1); nemaline myopathy (1); neuropathy (1); prediabetes (1); prostate carcinoma (1); schizophrenia (1); scoliosis (1); squamous cell carcinoma (1); Stroke (1); teratoma (1); type 2 diabetes mellitus (1).
A further 2 diseases each share a sentence with MYH2 in 1 paper.